PGBD4P1 (piggyBac transposable element derived 4 pseudogene 1)
Gene: Processed pseudogene on chromosome 7 (142,722,358 to 142,722,764, forward strand). Ensembl gene ENSG00000244273.
Diseases named in the same sentence as PGBD4P1 in open-access papers:
PGBD4P1 is named in the same sentence as 1 disease in open-access papers, as found by Europe PMC text mining. Sharing a sentence is not in itself a finding about the gene and the disease.
PGBD4P1 shares sentences with these, for which no sentence is quoted: schizophrenia (1 paper).